PDCD4 (programmed cell death 4)
Diseases named in the same sentence as PDCD4 in open-access papers (continued):
Sharing a sentence is not in itself a finding about the gene and the disease.
tumor (continued). "Increased miR-21 negatively regulates the tumor suppressor, PDCD4, by binding to its 3′-UTR, and this promotes tumor invasion, intravasation, and metastasis." (PMID 32967226, 2020). "Most studies of human PDCD4 have employed tumor cell lines, possibly resulting in a biased picture of its role in normal cells." (PMID 32066800, 2020). "Overall, these findings suggest that decreased expression of PDCD4, as seen in many tumor cells, similarly affects a plethora of cellular processes." (PMID 32066800, 2020). "This suggests that decreased PDCD4 expression contributes to tumor development and progression by compromising genomic integrity." (PMID 32066800, 2020). "As a novel tumour inhibitor, programmed cell death protein 4 (PDCD4) is involved in programmed cell death." (PMID 33089961, 2020). "PDCD4 was reported to be a tumor suppressor that was involved in cellular processes, such as antiproliferation, apoptosis, and antimetastasis in various cancer cells." (PMID 33072610, 2020). "It was found that PDCD4 mRNA expression was significantly decreased in tumorous tissues compared with that in adjacent normal tissues." (PMID 33078826, 2020). "It has been demonstrated that curcumin can inhibit tumor proliferation, invasion and metastasis by inhibiting the miR-21 transcription to stabilize the PDCD4 expression in CRC." (PMID 31620370, 2019). "PDCD4 is a novel tumor suppressor to show multi-functions inhibiting cell growth, tumor invasion, metastasis, and inducing apoptosis." (PMID 31075975, 2019). "According to the previous report and our prediction, plenty of tumor suppressor genes including PDCD4 and PTEN were confirmed as targets of miR-2133." (PMID 31666604, 2019). "One such tumor suppressor is programmed cell death 4 (PDCD4), which protects the cell from early neoplastic changes and is frequently downregulated in many cancers (2, –, 6)." (PMID 31235478, 2019). "PDCD4 is a tumor suppressor that inhibits the formation of pre-initiation complexes by combining with eIF4A." (PMID 30760284, 2019). "Recent studies have shown that the expression of PDCD4 is frequently silenced or reduced as a result of hypermethylation in tumor inflammatory microenvironment." (PMID 31035975, 2019). "Linc00472 (NCBI GeneID: 79940) is downregulated in CRC tissues and cells, and it acts as a tumor suppressor by upregulating PDCD4 by sponging miR-196a." (PMID 31620370, 2019). "To conclude, we show that PDCD4, a tumor suppressor gene suppressed in many cancers, is regulated through a relationship between miR-21 and miR-499." (PMID 31235478, 2019). "Since then, studies on PDCD4 have been accelerated and it becomes clear that PDCD4 is a multifunctional tumor suppressor." (PMID 31075975, 2019). "The regulation of PDCD4 by miR-21 and miR-499 typifies the complex partnerships that can exist between regulatory miRNAs when targeting mammalian tumor suppressor genes." (PMID 31235478, 2019). "One of the identified gene targets is programmed cell death 4 (PDCD4), a well-known tumor suppressor gene that promotes cell apoptosis and inhibits cell migration and proliferation." (PMID 31798638, 2019). "In their studies, MMP8 cleaved decorin, which inhibits TGF-β1: The subsequent downregulation of miR-21 expression led to activation of known tumor suppressors such as programmed cell death 4 (PDCD4)." (PMID 31514474, 2019). "A study of NPC tumor specimens found that tumor-suppressing protein PDCD4 suppresses the pPI3K/pAKT/c-JUN signaling pathway, which in turn modulates miR-374a's binding to CCND1, resulting in dysregulation of NPC cell growth, metastasis, and chemoresistance." (PMID 31456943, 2019). "Programmed cell death 4 (PDCD4), an important tumor suppressor, prevents neoplastic events and is commonly downregulated in cancer." (PMID 31235478, 2019).
tumor (continued). "Upregulation of PDCD4 expression in tumor cells increases the sensitivity for certain anti-cancer drugs, while downregulation of PDCD4 expression reduces the sensitivity for certain anti-cancer drugs." (PMID 30760284, 2019). "The tumor suppressor, programed cell death 4 (Pdcd4), inhibits the translation of Il10 transcripts and the secretion is enhanced in splenocytes in Pdcd4 knockout mice." (PMID 30816218, 2019). "Experiments to find a suppressor of the neoplastic transformation induced by the tumor promotors resulted in Pdcd4 suppressing AP-1 activation and TPA-induced neoplastic transformation in the JB6 cells." (PMID 31075975, 2019). "In this review, we focus on the suppression mechanisms of PDCD4 protein that is induced by the tumor promotors EGF and TPA, and in the inflammatory conditions." (PMID 31075975, 2019). "It has been reported that PDCD4 upregulation sensitizes tumor cells to anti-tumor drugs such as cisplatin, gemcitabine, geldanamycin and tamoxifen." (PMID 31075975, 2019). "PDCD4 expression is down-regulated or lost in several tumor types making it a promising molecular target for the treatment of some cancers." (PMID 31417117, 2019). "In HCCs, GAS5 acts as a tumor suppressor through the negative regulation of miR-21 and its target PDCD4 to suppress the migration and invasion of cancer cells." (PMID 31620370, 2019). "Pacritinib-mediated effects were accompanied by a reduction of oncomiR miR-21-5p, by which the tumor suppressor PDCD4 was targeted." (PMID 31269723, 2019). "More importantly, we provided evidence that miR-21-5p targets PDCD4, a tumor suppressor in both GBM cell lines." (PMID 31269723, 2019). "Overall, our findings indicate that lncRNA XIST can regulate HCC tumor growth through the miR-497-5p-PDCD4 axis." (PMID 31384173, 2019). "We found pacritinib treatment suppressed cell viability and colony/tumor sphere formation in association with decreased expression of STAT3, Sox2, PDCD4, and miR-21-5p and increased GFAP expression." (PMID 31269723, 2019). "We showed that pacritinib treatment significantly reduced cell viability and colony/tumor sphere formation in association with reduced levels of STAT3, Sox2, PDCD4, and miR-21; it also reduced the ability to generate M2 GAMs." (PMID 31269723, 2019). "It is well documented that miR-21 targets tumor suppressors such as PDCD4 and phosphatase and tensin homolog (PTEN), both of which suppress expressions of PI3K, STAT3, mTOR, and β-catenin." (PMID 31878245, 2019). "PDCD4 is involved in regulating apoptosis, is located on human chromosome 10q25.2 and is considered a novel tumor suppressor gene." (PMID 31384173, 2019). "Programmed cell death 4 (PDCD4) is a tumor suppressor gene involved in cell apoptosis, transformation, invasion and tumor progression." (PMID 31409387, 2019). "Western blot analysis revealed that TUG1 knockdown or DDP exposure pointedly increased PDCD4 protein level in tumor tissues." (PMID 30519392, 2018). "MAPK15 is a novel HuR kinase that regulates tumor suppressor PDCD4 through a miR-21 dependent mechanism." (PMID 30524968, 2018). "The overexpression of miR-21 down-regulated the expression of tumor suppressors such as PDCD4 and TIMP3 and promoted cell proliferation, leading to the development of PC." (PMID 29385987, 2018). "Mechanically, Linc00472 acted as a tumor suppressor in CRC by up-regulating PDCD4 via sponging miR-196a." (PMID 29930217, 2018). "SRSF3 represses the expression of programmed cell death 4 (PDCD4) protein, which is a tumor suppressor involved in apoptosis, and PDCD4 down-regulation is a potential marker for solid tumor prognoses." (PMID 30279379, 2018). "Silencing HNRNPC leads to reduced phosphorylation of AKT at Ser473 resulting in diminished PDCD4 phosphorylation and suppressed tumour function." (PMID 29899543, 2018).
tumor (continued). "In this latter study, it was shown that PDCD4 methylation promotes tumor cell viability during nutrient deprivation, and that this process is reversed upon recovery from starvation through phosphorylation of PDCD4 and it translocation to the nucleus." (PMID 30613353, 2018). "PDCD4 has been demonstrated to be dramatically down-regulated and act as a tumor suppressor in various cancers." (PMID 29930217, 2018). "A previous study showed that miR-21 regulates beta-cell death by targeting the tumor-suppressing gene Pdcd4." (PMID 28747214, 2017). "Programmed cell death 4 (PDCD4) is a novel tumor suppressor gene involved in inhibiting neoplastic transformation, and invasion, and tumor progression." (PMID 28881718, 2017). "MiR-21 is one of the most frequently over expressed miRNAs in cancer, and it exerts its anti-apoptotic effects by targeting the tumor suppressors PDCD4 and PTEN in Certain types of cancer, but there is no definite conclusion in EC." (PMID 27885434, 2017). "PDCD4, a novel tumor suppressor gene, is involved in apoptosis, and deletions in or reduced expression of PDCD4 have been found in many human malignant tumor tissues and cells." (PMID 28423589, 2017). "Human PBMCs treated with LPS observed an upregulation of miR-21 and a lower protein programmed cell death 4 (PDCD4) expression, which is a proinflammatory tumor suppressor and known target of miR-21." (PMID 29077020, 2017). "As an important tumor suppressor, we know much about its involvement in carcinogenesis, but little about the upstream regulators of PDCD4." (PMID 28854977, 2017). "Curcumin inhibited miR-21 expression, tumor growth, invasion and in vivo metastasis, and stabilized its tumor suppressor target Pdcd4 in CRC cells." (PMID 28424679, 2017). "As a tumor suppressor, PDCD4 inhibits tumor progression and neoplastic transformation, while miR-21 restrains the functions of PDCD4 by directly suppressing its expression." (PMID 28061475, 2017). "Consistent with tumor volume data, relatively less miR-21 level and more PDCD4 expression were observed in xenograft tumors generated with BEAS-2B cells chronically co-treated with quercetin and Cr(VI)." (PMID 28881718, 2017). "It has been shown that PDCD4, a novel tumor suppressor is an important functional target of the oncogenic microRNA miR-21." (PMID 28881718, 2017). "Most of targets for miR-21 have been identified as tumor suppressors, such as PDCD4 (Programmed cell death 4), PTEN, RECK, TP63 and FASLG." (PMID 29190966, 2017). "By inhibiting PDCD4, miR-21 acts as an anti-apoptotic factor and promotes tumor cell transformation." (PMID 28423589, 2017). "Mir-21 regulates the expression of PDCD4 (programmed cell death protein 4), a tumor suppressor identified through a proteomics approach." (PMID 29100302, 2017). "In the case of miR-21, a number of targets have been experimentally validated, and most of them are tumor suppressors; notable targets include PDCD4, FasL, and PTEN." (PMID 29212210, 2017). "miR-21, an oncomir, regulates Phosphatase and tensin homolog (PTEN), this enzyme acts as a tumor suppressor, it has an inverse relation with programmed cell death protein 4 (PDCD4) expression and it exerts an inhibitory effect on cancer cell proliferation." (PMID 28245631, 2017). "MiR-21 has been shown to affect cell proliferation, invasion, and the clinical outcome by downregulating the expression of tumor suppressors, such as PDCD4, TIMP3, RECK, and KRIT1." (PMID 28466015, 2017). "Programmed cell death 4 (PDCD4), a new tumor suppressor, has been documented to be a potential diagnostic tool and treatment target for neoplasia due to the inhabitation of tumor promotion/progression and metastasis." (PMID 27279541, 2016). "Intriguingly, a previous study reported animportant functional linkage between miR-21 and tumor suppressor PDCD4, by which theoverexpression of miR-21 can contribute to inhibition of PDCD4 and its tumor-suppressivefunctions." (PMID 27240294, 2016).
tumor (continued). "The tumor suppressor PDCD4 has also been shown to be regulated by AKT but at position S67 controlling its localization." (PMID 27909043, 2016). "The results showed that, as compared to controls, the expression of Bak, ZBP-89 and PDCD4 was dramatically increased in tumor cells over-expressed HIF-2α." (PMID 27119229, 2016). "Tumor growth was enhanced when SCC13 cells were injected into mouse back skin with HDFs with PDCD4 gene silencing." (PMID 27542230, 2016). "Programmed cell death 4 (PDCD4) is a novel tumor suppressor gene that has been known as a promising target for future anticancer therapies for several years." (PMID 27634902, 2016). "Since stabilization of Pdcd4 emerged as an interesting concept for novel tumor therapeutics, we set out to identify novel Pdcd4 stabilizers." (PMID 26982744, 2016). "gga-miR-21 was also found to promote tumor formation by targeting the chicken programmed cell death 4 (PDCD4) mRNA." (PMID 27800484, 2016). "The cell proliferation rate measured by the percentage of Ki-67-positive tumor cells was decreased in the group implanted with the PDCD4 overexpression plasmid and increased in the group implanted with the miR-93 overexpression lentivirus." (PMID 27021515, 2016). "We also showed that miR-208a-3p promoted the development of tumor growth in xenograft mice by negatively regulating PDCD4." (PMID 27634902, 2016). "In this context, mucin 1 (MUC1), an oncoprotein that is aberrantly expressed in human cancers, is a translational target of PDCD4, suggesting that PDCD4 acts as a tumor suppressor by inhibiting oncoprotein translation." (PMID 27542230, 2016). "BEAS-2B cells with miR-21 knock down also blocked the suppression of its target tumor suppressor, PDCD4 that normally occurs with chronic Cr(VI) treatment." (PMID 27323401, 2016). "For example, miR-21 binds to a conserved site within the 3′-untranslated region of mRNA of the program cell death 4, PDCD4 (a tumor suppressor protein) leading to PDCD4 downregulation and tumor cell invasion and metastasis." (PMID 27070574, 2016). "Down-regulation of PDCD4 expression by miR-21 leads to tumor cell growth, survival, chemoresistance, invasion and metastasis." (PMID 27323401, 2016). "Secondly, the tumor suppressor, programmed cell death 4 (PDCD4), has been shown to inhibit the translation machinery by binding to the translational initiation factor eIF4A." (PMID 28721382, 2016). "We have further shown that the tumor suppressor PDCD4 is lost in the majority of tonsil SCCs and PDCD4 is directly regulated by two miRNAs." (PMID 26867589, 2016). "PDCD4 is widely recognized as an important tumor suppressor, as its expression is dramatically downregulated in many cancer types, including CRC, lung cancer, breast cancer and gastric cancer." (PMID 27647131, 2016). "Some studies have found a task for PDCD4 as a tumor oppressor that is missed in definite aggressive malignancies." (PMID 27275325, 2016). "PDCD4 is a novel tumor suppressor reported to inhibit neoplastic transformation, tumor promotion and progression." (PMID 27323401, 2016).
tumor (continued). "Programmed cell death 4 (PDCD4) is a novel tumor suppressor gene and a promising target for anticancer therapies." (PMID 27634902, 2016). "During tumor progression, PDCD4 protein translocation from the nucleus to the cytoplasm was observed in cancer cells." (PMID 27852288, 2016). "PDCD4 is a tumor suppressor gene involved in apoptosis, cell transformation, invasion and tumor progression." (PMID 26864640, 2016). "To explore the esophagus-specific functional relationships for Fbxw7, Stk40, and Pdcd4 (tumor-suppressor targets of miR-223, -31, -21), we employed FNTM for the rat." (PMID 26918602, 2016). "Earlier studies showed that PDCD4, a novel tumor suppressor is an important functional target of the oncogenic microRNA miR-21." (PMID 27323401, 2016). "As a famous tumor suppressor gene, PDCD4 was described as inhibitor of cancer cell migration and metastasis in different cancer forms including LSCC." (PMID 27533461, 2016). "Oncogenic miR-21 exerts its anti-apoptotic effects by targeting the tumor suppressors PDCD4 and PTEN." (PMID 26918602, 2016). "The percentage of Ki-67-positive tumor cells was increased in the group implanted with miR-181b lentivirus and decreased in the group implanted with PDCD4 plasmid." (PMID 27647131, 2016). "The mechanism by which miR-21 promotes tumor invasion and metastasis is associated with its ability to repress multiple tumor suppressor genes, including tropomyosin 1 (TPM1), programmed cell death 4 (PDCD4), and maspin." (PMID 26769851, 2016). "The expression levels of miR-21 and miR-499 are known to control the translation of the tumour suppressor PDCD4 and let-7 has been shown to regulate Dicer levels." (PMID 26867589, 2016). "PDCD4 is a novel tumor suppressor gene, and its protein product plays a role in suppression of tumorigenesis and tumor invasion." (PMID 27634902, 2016). "For example, miR-21 has been repeatedly reported to facilitate tumor progression through targeting assorted tumor-suppressors, such as Bcl-2, PDCD4 and PTEN." (PMID 27006642, 2016). "PDCD4, a tumor suppressor gene, is involved in cell apoptosis,transformation, invasion, as well as tumor progression." (PMID 27240294, 2016). "Silencing of PDCD4 in these cells reproduces the effects of loss of CSL, leading to induction of cellular senescence and conversion into CAFs with tumor enhancing properties." (PMID 27542230, 2016). "It is consistently dysregulated in many types of cancer and is a key factor in tumorigenesis and tumor suppression because it targets tumor suppressor genes such as tropomyosin 1, programmed cell death 4, and phosphatase and tensin homolog." (PMID 25706383, 2015). "We identified the tumor suppressor Pdcd4 as IBtkα interactor and ubiquitylation substrate of CRL3IBTK for proteasomal degradation." (PMID 25882842, 2015). "We also identified the Pdcd4 (programmed cell death 4) protein, a well known tumor suppressor involved in several cellular processes." (PMID 25882842, 2015). "Although PDCD4 was systematically elucidated as a tumor suppressor in various tumors, the normal biological function of PDCD4 is unclear." (PMID 26703592, 2015). "As shown by anti-miR treatment of TNBC cells, endogenous miR-206 directly repressed the translation of the tumor suppressors PDCD4 and CX43 and promoted tumor cell survival, chemoresistance and in vivo tumor initiation." (PMID 26053033, 2015). "Our results suggest that tumor suppressor PDCD4 is uniquely induced in a cell density-dependent manner in keratinocytes and serves as a regulator of keratinocyte cell proliferation and contact inhibition in vitro." (PMID 26703592, 2015). "PDCD4 was originally identified as a gene whose expression is induced in various types of apoptosis, and subsequently identified as a tumor suppressor in the JB6 mouse epidermal cell line model." (PMID 26703592, 2015). "In this study, for the first time, we find that tumor suppressor PDCD4 is uniquely induced in a cell density-dependent manner in keratinocytes." (PMID 26703592, 2015).